BMP4 (bone morphogenetic protein 4)
Diseases named in the same sentence as BMP4 in open-access papers (continued):
Sharing a sentence is not in itself a finding about the gene and the disease.
tumor (continued). "We also analyzed the methylation level of BMP4 promoter in 30 HCC patients, and found that the methylation level of the BMP4 promoter in adjacent tissue is much higher than in tumor tissue, and lower methylation level in HCC tissue was associated metastasis." (PMID 30718464, 2019). "The notion that BMP4 enforces tumor dormancy is supported by its ability to block in-vitro tumor sphere formation, to diminish the expression of Nanog, Sox2, and Taz, and increase that of GATA3." (PMID 31547567, 2019). "Conversely, Bmp4 is a known inhibitor of angiogenesis; thus, its downregulation probably contributes to 4C11+ tumor vascularization." (PMID 31069961, 2019). "As compared with the si-NC group, BMP4 knockdown resulted in a significant decrease in tumor weight and a remarkably smaller tumor volume (p < 0.01, respectively)." (PMID 30012194, 2018). "Our previous studies have found that BMP4 acted as a tumor promotion protein by facilitating HCC proliferation, invasion and chemoresistance, as well as identified its prognostic value in HCC patients." (PMID 30012194, 2018). "Emerging bodies of evidences indicate that the dysregulation of BMP4 has promoting effects on tumor proliferation, metastasis and drug-resistance." (PMID 30012194, 2018). "This was confirmed by BMP4 immunoreactivity in tumor cells of metastases with ongoing bone formation, as determined by histological evaluation of van Gieson-stained sections." (PMID 29670000, 2018). "In the current study, we identified the tumor cells as the predominant source of BMP4 in metastasis with ongoing bone formation, while the cell origin of BMP2 was not examined." (PMID 29670000, 2018). "The BMP4 staining intensity of tumor cells varied between 0 and 3 and the distribution between 0 and 4, giving immunoreactive scores (IR scores) in the range of 0–12." (PMID 29670000, 2018). "More interestingly, in the two DJ-1 low-expressing paired CRC samples, the BMP4 expression was markedly decreased in CRC compared with non-tumor tissues." (PMID 30158634, 2018). "αSMA expression in stromal-fibroblasts showed inverse relationship with proliferation of cancer cell population and a positive relation with frequency of stem-like cancer cell in gingivobuccal primary tumor samples and in vitro assays, in BMP4-mediated manner." (PMID 30287850, 2018). "We then assessed the effect of BMP4 stimulation on cell migration in a panel of cancer cell lines with a predicted migratory and non‐migratory line from each tumour subtype." (PMID 28299802, 2017). "Role of DNA methylation in BMP4 regulation in tumor brain and chemo brain needs to be further substantiated in the large-scale studies." (PMID 28758896, 2017). "It has been previously shown that Bone Morphogenetic Protein 4 (BMP4) activates the Smad signaling cascade and induces differentiation of stem-like, tumor-initiating precursors of GBMs and that SMADs and Jmjd3 co-regulate genes in NSCs." (PMID 28384648, 2017). "In HCC, the inhibition of the BMP-4/SMAD1 signaling has been reported to suppress tumor migration, invasion, and EMT." (PMID 27661009, 2016). "Our study indicates that hNSCs can deliver BMP4 that can be released from hNSCs to achieve tumor inhibitive effects and to extend animal survival." (PMID 26908439, 2016). "Cells were harvested from their respective chambers (CA-MSCs in the upper well, tumor cells in the lower well) and analyzed via qRT-PCR to determine levels of BMP4 in CA-MSCs and HH in tumor cells." (PMID 26755648, 2016). "In summary, the identification of a signaling loop with tumor derived HH and CA-MSC derived BMP4 adds further support to the importance of the tumor microenvironment and stromal signaling." (PMID 26755648, 2016). "Treatment with IPI-926, a SMO inhibitor, significantly decreased the TCM-mediated induction of BMP4 transcription and BMP4 protein levels suggesting activation of BMP4 expression is via tumor cell produced HH ligands." (PMID 26755648, 2016).
tumor (continued). "This points to a tumor/CA-MSC HH/BMP4 signaling loop as a critical mediator of the pro-tumorigenic effects of CA-MSCs." (PMID 26755648, 2016). "Consistent with prior studies, our data also demonstrate a modest increase in ALDH+ tumor cells after co-growth with normal adipose-derived MSCs (which at baseline have significantly lower levels of BMP4 compared to CA-MSCs)." (PMID 26755648, 2016). "GREM1 and the BMP ligand BMP5 were enriched significantly in the stromal fraction, in keeping with the results from the mouse model, whereas tumour cells expressed BMP4 in several cases." (PMID 27492255, 2016). "In other solid tumors, BMP-4 paraclinically inhibits tumor angiogenesis via the induction of thrombospondin-1 (TSP-1)." (PMID 27661009, 2016). "In an attempt to explore the contributions of macrophages for BMP4 produce in tumor-stress conditions, we analyzed colocalization of BMP4 and F4/80 by confocal immunofluorescence." (PMID 25822717, 2015). "Of interest, our results indicate that splenic macrophages synthesize bone morphogenetic protein 4(BMP4) in response to tumor stress." (PMID 25822717, 2015). "We have clearly demonstrated here that BMP4 is indirectly suppressed by miR-200 and that BMP4 promotes tumor cell migration/invasion and metastasis." (PMID 26395571, 2015). "We also found five TSG-type genes that were thought to act as tumor suppressor genes because they exhibited DNA methylation features similar to those observed in the BMP4 and IGFBP3 genes." (PMID 26421064, 2015). "This situation is reminiscent of what has been reported about activation of BMP2- and BMP4-dependent pathways in other tumor types." (PMID 26337467, 2015). "Tumor progression of these mice led to increased amounts of bone morphogenetic protein 4 (BMP4) in spleen." (PMID 25822717, 2015). "It has been reported that RA- and RA/BMP-4 induced apoptosis in different tumor cells is related with an up-regulation and / or activation of caspase-3." (PMID 26173116, 2015). "Our results provide insight that macrophages and BMP4 are positive regulators of splenic erythropoiesis in tumor pathological situations." (PMID 25822717, 2015). "In primary tumors, BMP4 promoter methylation levels were inversely correlated with BMP4 expression, and GC patients with high BMP4 expression in tumor exhibited significantly worse prognosis." (PMID 26380657, 2015). "intracranial inoculation of the BMP4-virus at the same coordinates as the tumor cells (implanted two weeks earlier) resulted in a rapid tumor regression and improved survival of the mice." (PMID 24877113, 2014). "The virus overexpressing BMP4 promoted cell differentiation of primary GIC cultures derived from tumor biopsies." (PMID 24877113, 2014). "The authors therefore suggest that BMP4 is playing a tumor suppressor role in LSCC, while SOX2 repression of BMP4 transcription causes cell growth." (PMID 25114775, 2014). "The association between the BMP-4 genotype and the BMP-4 protein expression in tumor samples was analyzed." (PMID 24779016, 2014). "By both WB and RTqPCR analysis, they showed that BMP4 expression was significantly lower in tumor tissue than in adjacent healthy tissue." (PMID 24877113, 2014). "Univariate analysis showed that low BMP4 levels correlated with high expression of the cell cycle marker Ki67, as well as with high tumor grade (P < 0.001 for both correlations)." (PMID 24877113, 2014). "Most importantly, the Vescovi group also demonstrated that in vivo delivery of BMP4 inhibits tumor growth." (PMID 24877113, 2014). "Similar to the mouse experiments BMP4 stimulation increased MCF7 tumor cell invasion and was reduced with the BMP receptor inhibitor DMH1." (PMID 23840733, 2013). "The expression of BMP4 in tumor tissues was significantly lower than that in the paracancer tissues at both mRNA and protein levels (P = 0.01 and 0.001, respectively)." (PMID 24099560, 2013).
tumor (continued). "The resulting effect of a BMP-4 expressing VACV infection causes an enhanced growth inhibition of GBM stem cells in vitro and substantial tumor regression in mice compared to the parental, non-BMP-4 carrying VACV." (PMID 23800258, 2013). "During this process, we have further confirmed the utility of these primary CSC-enriched systems for drug discovery and introduced real time imaging to monitor effects of the BMP-4 VACV on tumor growth." (PMID 23800258, 2013). "RT-PCR analysis of high-grade (WHO III-IV) and low-grade (WHO I-II) tumor tissues showed that BMP4 mRNA expression was significantly lower in tumor tissues than in paracancer tissues." (PMID 24099560, 2013). "Morphological changes of the cells were also evident; fibroblasts stimulated by BMP4 altered tumor cells to appear more spindle-like and dysplastic when compared with controls and DMH1 treated fibroblasts." (PMID 23840733, 2013). "The key regulatory subunit, the bone morphogenetic protein 4 (BMP4), is overexpressed and associated with tumor metastasis in a variety of cancers." (PMID 23590708, 2013). "The heightened level of replication and BMP-4 production leads to excellent tumor growth inhibition and survival of mice implanted with GBM CSCs." (PMID 23800258, 2013). "Of the 16 tumor-normal pairs with presumed hypermethylated promoter loci in HCC (in genes BMP4, RASSF1,GSTP1, and TACSTD2), 5, 6, 14 and 16 of the 16 HCCs had decreased expression of the gene, respectively." (PMID 23437062, 2013). "Since potent developmental regulators are frequently disrupted in cancer, it is to be expected that BMP4 also contributes to tumor development." (PMID 23590708, 2013). "On the other hand, we showed that both the CDSF medium used in the present study, which contains LIF, and the CDSF medium supplemented with Bmp4 poorly sustained the tumor-like growth of mESCs." (PMID 21731714, 2011). "Because of the following two observations, we consider the effect of Bmp4 on Gsk3β or the tumor-like growth of mESCs antagonistic or indirect." (PMID 21731714, 2011). "The expression levels of bone morphogenetic proteins 2 and 4 (BMP2 and BMP4), both have been suggested to play important roles in tumour metastasis, showed a 10 and 14 fold decrease by rosiglitazone, respectively." (PMID 20226009, 2010). "BMP4 has shown some promise as a potential targeted therapy for GSCs, inducing differentiation of GSCs - increasing radiosensitivity and reducing overall tumor burden in in vitro and in animal studies, and recently has been shown to be safe in a phase I clinical trial." (PMID 41279885, 2025). "Besides, high levels of CHRDL1 inhibited BMP4-induced Smad1/5/8 phosphorylation, thereby suppressing tumor growth." (PMID 40837015, 2025). "It had been reported that it could activate the EMT process by regulating the expression of E-cadherin, Snail and ZEB through BMP4, thereby inducing tumor metastasis." (PMID 40881692, 2025). "These contradictory findings suggest that the effect of BMP4 on cancer growth and migration may be dependent on the tumor subtype and requires further assessments." (PMID 40001874, 2025). "For example, neither tumoural nor stromal BMP4 showed any trend in association with the number of lymph node metastases or tumour size." (PMID 40826447, 2025). "Indeed, we have shown previously that BMP4 can suppress the number and activity of myeloid derived suppressor cells in the tumor microenvironment." (PMID 38689334, 2024). "In addition, we still cannot explain why BMP4 acts to drive tumor progression in some other cancer types, since SMAD4 status appears to not be the major factor." (PMID 38689334, 2024). "However, a tumor-promoting effect of BMP4 is reported in other tumor types, especially when SMAD4 is inactive." (PMID 38689334, 2024). "Consistent with our hypothesis, when SMAD4 activity was reduced by two different shRNA constructs, enforced BMP4 accelerated tumor growth in the 231-HM tumor model." (PMID 38689334, 2024).
tumor (continued). "Recovery of the tumour cells from the primary tumours by enzymatic disaggregation and flow cytometry based on their expression of TurboGFP allowed for selective analysis of the influence of BMP4 on gene expression in vivo." (PMID 39273106, 2024). "However, studies have also reported that monotherapy with BMP4 had only temporary effects and can also induce senescence of proliferation-competent tumor cells, thus contributing to therapy resistance." (PMID 39337661, 2024). "Transcriptomic analysis of cancer cells recovered from primary tumours and phosphoproteomic analyses of cancer cells exposed to recombinant BMP4 revealed that BMP4 inhibits cholesterol biosynthesis, with many genes in this biosynthetic pathway being downregulated by BMP4." (PMID 39273106, 2024). "However, a tumor-promoting role for BMP4 has been reported in other cancer types, potentially through the induction of epithelial-to-mesenchymal transition (EMT)." (PMID 38689334, 2024). "Notably, results showed that tumor grade (p = 0.010) and IQGAP3/BMP4 (p = 0.004) were independent risk factors for progression." (PMID 38668066, 2024). "We have previously shown that tumor-induced bone formation is due to tumor-secreted BMP4." (PMID 39061241, 2024). "In addition, BMP4 promotes the differentiation of urothelial cells and, interestingly, inhibits proliferation while promoting differentiation in tumor cells." (PMID 39606239, 2024). "The lack of profound suppression of cholesterol biosynthesis genes by BMP4 in vitro compared to that observed in primary tumours could be due to differences in the basal expression of these genes." (PMID 39273106, 2024). "Non-canonical signalling pathways involved in this promotion of tumor growth may explain the contradictory effect of BMP4 in regulating tumor progression that has been reported by others." (PMID 38689334, 2024). "To identify causes of the adverse effects of non-canonical BMP4 signalling, we completed RNA sequencing analysis of 231-HM cells recovered from an in vivo tumor microenvironment." (PMID 38689334, 2024). "We have reported previously that BMP4 secretion from tumor cells suppresses the activity of myeloid-derived suppressor cells (MDSCs) and may thereby promote anti-tumor immune responses through paracrine signalling from BMP4 expressing tumors." (PMID 38689334, 2024). "Furthermore, in breast cancer, the BMP4–SMAD7 signalling axis blocks tumour metastasis, and increased levels of BMP4 and SMAD7 predicted improved recurrence-free survival and OS in breast cancer patients." (PMID 37685308, 2023). "Amongst the novel BMP4 targets identified were the transcript encoding the dual histone demethylase, KDM7A, previously shown to promote tumour growth and mediate androgen receptor activity, and FGF4; both were upregulated in both cell lines following BMP4 stimulation." (PMID 37048077, 2023). "Using a xenograft model of HCC, we found that BMP4 promoted glycogen accumulation and tumor growth, which could be effectively blocked by BAY-876." (PMID 37443106, 2023). "On the other hand, BMP4 inhibits tumor growth by interacting with other cytokines." (PMID 35401213, 2022). "Additional studies on the BMP4/BMPR signaling pathway in a large number of different primary cells/cell lines from each tumor type are further needed to clarify the exact contribution of BMP4 signaling to tumorigenesis and metastasis in a tissue-specific manner." (PMID 35694408, 2022). "Whether the inhibition of BMP4 upregulated cell proliferation genes will benefit the tumor suppressor roles of BMP4 in GBM treatment remains to be elucidated." (PMID 36316503, 2022). "Furthermore, in some tumor types, such as pituitary adenomas, BMP4 plays cell type-specific roles—it stimulates pituitary prolactinoma while inhibiting corticotroph tumor cells." (PMID 35694408, 2022). "The BMP-4 has also been used as tumor-suppressing agent in MSC engineering for cancer therapy." (PMID 35631698, 2022).
tumor (continued). "Thus, in general, the consequences of BMP4 activation in the tumor microenvironment are likely dependent on cellular composition and the context-specific BMP4 signaling within a particular cell type." (PMID 35694408, 2022). "Moreover, treatment of Renca cells with 30 ng/mL BMP4 for 7 days markedly inhibited tumor sphere formation which was reversed by overexpression of LAPTM5." (PMID 35842443, 2022). "Indeed, BMP4 secretion by BC cells provides the M2 signal necessary for a pro-tumoral immune environment, which translates into cytokine production favoring tumor progression." (PMID 35053451, 2022). "A 2005 study demonstrated that BMP4 is a key regulator of tumor proliferation in GBM." (PMID 34012965, 2021). "It is not easy to explain, why the decreased levels of these two markers: TSP-1 and BMP-4 might promote tumor development, because the role in cancer progression of these two analyzed markers remains unclear." (PMID 34501309, 2021). "Experience in the other neoplastic diseases indicate the BMP-4 importance." (PMID 34501309, 2021). "Bone morphogenetic protein-4 (BMP-4) expression is reduced in HEVs of tumor-draining LNs." (PMID 34241649, 2021). "This evidence indicated the possibility that in NSCLC, upregulated SUV39H1 may contribute to tumor progression by regulating BMP4." (PMID 33472665, 2021). "CAF with tumor-promoting functions secrete growth factors (HGF, IGF1, CTGF, PDGF, VEGF, LIF), cytokines (IL-1, IL-4, IL-6, IL-8, IL-10, TGF-β), and chemokines (CCL2, CCL5, CXCL5, CXCL9, CXCL10, CXCL12), WNT5α, and bone morphogenic protein 4 (BMP4), which promote tumor progression." (PMID 35008832, 2021). "Effectiveness of BMP-4 in inhibition of the tumor growth was lower in TSP-1 knockdown cancer cells." (PMID 34501309, 2021). "Their results showed that IQGAP3/BMP4 overexpression was observed in higher-stage and higher-grade diseases with high risks of recurrence and progression, whereas IQGAP3/FAM107A overexpression was associated with larger tumor size and disease progression." (PMID 33672869, 2021). "Moreover, the expression of BMP4 is higher in NSCLC tumors than that in paired adjacent non-tumor tissues." (PMID 33472665, 2021). "However, to fully elucidate BMP4 therapeutic potential, differential roles of BMP4 in tumor molecular subgroups should be examined." (PMID 32102285, 2020). "In addition, ZFP90 transcriptionally represses the expression of a tumor suppressor, BMP4, and mediates tumorigenesis." (PMID 31641208, 2020). "Similarly, mouse glioblastoma stem cells when treated with BMP4 protein differentiates into Gila, resulting in reduced tumor growth, and tumor initiation capacity of CSCs upon transplantation." (PMID 33233552, 2020). "Moreover, CHRDL1 antagonizes the function of BMP4 by binding to it and preventing its interaction with receptors, resulting in tumor-suppressing effects in patients with BC." (PMID 32775417, 2020). "Tumor formation was accelerated using BMP-4-treated MDA-MB-231 cells compared to control cells." (PMID 31409851, 2019). "In agreement with real-time PCR arrays, BMP4 was highly expressed in tumor sections." (PMID 31013771, 2019). "Moreover, BMP4 function as tumor suppressor in in-vitro and orthotopic models of glioblastoma multiforme, where it limits tumor cell migration and invasion via SMAD1/5/8 mediated enhancement of E-cadherin and claudin expression." (PMID 31547567, 2019). "On the other side, BMP4 has been shown to increase cell migration and invasion of tumor cells." (PMID 31694641, 2019). "On one side, it has been demonstrated that BMP4 inhibits tumor cell growth." (PMID 31694641, 2019). "In addition to BMP4, also elevated levels of other members of the BMP-family, including BMP6 and BMP7, have been linked to increased tumor aggressiveness." (PMID 31694641, 2019).